CD86 (CD86 molecule)
Diseases named in the same sentence as CD86 in open-access papers (continued):
Sharing a sentence is not in itself a finding about the gene and the disease.
infection (continued). "We found strongly reduced levels of CD86 expression on CD11c+ cells at critical early time points after infection in both pregnancy and estrogen-treatment, suggesting a deficiency in proper DC maturation." (PMID 22792357, 2012). "Effects of sex, age group and infection status on mDC and pDC proportions and levels of HLA-DR, CD86 expression on both subsets." (PMID 23029585, 2012). "DCs infected with live H37Ra displayed a mature phenotype, up-regulating CD83 and CD86 after 48 h infection with Mtb." (PMID 22024399, 2011). "When MAR-5A3 was administered on day 4 after WNV-NY infection and splenocytes analyzed on day 9, we also observed a decrease in surface expression of CD86 on CD11b+ (P<0.05) and CD11c+ (P<0.007) cells relative to the control MAb treatment." (PMID 22144897, 2011). "In vivo, however, the infection induced the expression of the co-stimulatory molecules CD86 and CD80 as well as MHC class II by CD11c+ cells in wild type and TLR2/4 double-deficient mice with comparable efficiency." (PMID 22096480, 2011). "Both cDCs and moDCs infected with NYVAC-C-ΔB19R showed increased CD86 expression 48 hours after infection." (PMID 21347234, 2011). "Microglia display differential expression patterns of antigen presentation molecules, I-As, H-2Ks, CD80, CD86, but express elevated and sustained levels of B7-H1 as early as day 3 post-infection compared to sham-infected microglia." (PMID 21494618, 2011). "Microglia also display differences in CD80 and CD86 expression following TMEV infection in vivo, which differs from the expression patterns observed with our in vitro studies in that upregulation is delayed." (PMID 21494618, 2011). "We compared BMDM obtained from fresh and frozen BM cells and found that both are similarly able to trigger the expression of CD80 and CD86 in response to LPS or infection with the intracellular bacteria Legionella pneumophila." (PMID 21179419, 2010). "CD86 was initially elevated on B cells in both strains, then decreased in C57Bl/6 mice and increased in Balb/c mice at d28 post-infection." (PMID 20625554, 2010). "IL-4 can also act on APCs to polarize them during an active infection and it has been shown to up-regulate CD86 on human alveolar macrophages via ERK1/2 and JAK/STAT6 pathways." (PMID 21054882, 2010). "Expression of the costimulatory molecules CD80 and CD86 was markedly increased in all animals at 2 weeks post infection indicative of rapid mDC activation." (PMID 21203477, 2010). "MHCII and costimulatory molecules CD40, CD80, and CD86 had an average 0.5 fold decrease in their MFI intensity from three to ten weeks after infection." (PMID 20625513, 2010). "CD86 was increased post-infection in both models, but with different profiles (p = 0.0001, 2-way ANOVA)." (PMID 20625554, 2010). "To determine if F-MLV causes activation of specific DC subsets during infection, we infected C57BL/6 mice with F-MLV and examined the expression of CD80 and CD86 on all three splenic DC subsets at different times post-infection." (PMID 19214214, 2009). "The results were consistent with our earlier findings; CD80 expression was reduced from 41% to 35% after LV-PLAP infection, while CD86 expression was reduced from 61% to 49%." (PMID 15518595, 2004). "Furthermore, primary monocytes expressed CD80, CD86, and HLA-DR upon direct infection or through potential paracrine stimulation." (PMID 41280933, 2025). "Additionally, in both BMDM types, CD86 expression was higher at 2 h and 1 day after infection than in the naive state; however, on the second day, the expression level decreased below that of naive BMDMs." (PMID 40391046, 2025). "Post-infection, all genotypes increased CD86 expression on Tim4+ macrophages." (PMID 40791464, 2025).
infection (continued). "Following nanobody intervention, both the quantity and function of DCs and NK cells showed dose-dependent recovery compared with the infection group: not only were the numbers of DCs and NK cells restored, but the expression of CD86 on DCs was also Considerably upregulated." (PMID 41441659, 2025). "Previous work has demonstrated that cd86 and cd80 are upregulated at the transcriptional level to a greater extent during MP-12 infection of microglia versus ZH501 at 4 h post infection, which may be a downstream effect of lower-type I IFN induction by ZH501." (PMID 38392897, 2024). "However, in contrast to LPS stimulation, infection with S. aureus led to a significant reduction of CD86+ cells to, on average, less than 15% in WT BMDM." (PMID 37982695, 2024). "A similar result was shown in the infection of BMDC with L. infantum, where the inhibition of PI3K/Akt by wortmannin before BMDC infection caused a slight increase in the transcription of costimulatory molecules CD40 and CD86." (PMID 38787051, 2024). "The resulting activation state, which was maintained up to 96 h post-infection, as characterized by detectable levels of viral E and NS1 proteins, as well as by CD11b, CD11c, CD80, and CD86, which are proteins associated with a pro-adherent phenotype and pro-inflammatory state." (PMID 38247836, 2024). "Furthermore, we observed the proinflammatory M1-type activation in monocytes, with a significant increase in the MFI of CD86 expression at 6 h, 12 h, and 24 h post-infection." (PMID 38951957, 2024). "Only in the infected mice, we detected neutrophils included within cluster 30 (Siglec-Hlow PD-L1- CD86-), this subpopulation was reduced at 48 and 72 h post infection (p<0.05, between the numbers at 48 and 72 h post infection versus the 24 h post infection; one-way ANOVA)." (PMID 38578798, 2024). "Since CD80 and CD86 are required for further T cell activation, increased expression would also likely result in enhanced T cell activation and more rapid clearance of infection in vivo." (PMID 37213504, 2023). "Similarly, we observed that switched memory B cells had significantly increased expression of CD86 and a significant loss of CD21 with severe SARS-CoV-2 infection compared to mild infection, vaccination, or healthy controls." (PMID 37638016, 2023). "The expression of pro-inflammatory cytokines, but not M1 surface marker CD86, is likely associated with the acute microglial response occurring in the early phases of infection, also testified by the lack of TMEM119 downregulation." (PMID 36781876, 2023). "Interestingly, we observed that the enhanced CD80+ CD86+ macrophages in colon tissues derived from mice with translocated infection were in line with the lower levels of secretion of TNF-α." (PMID 36445086, 2022). "The expression of CD86 is increased in the majority of early infection phases." (PMID 36444627, 2022). "Importantly, more CD80+ CD86+ macrophages existed in colon tissues harvested from CRKP-colonized mice with translocated infection." (PMID 36445086, 2022). "We then investigated whether such trogocytosis of CD80 and CD86 by CD8+ T cells was merely an in vitro phenomenon or whether it also occurred upon infection in vivo." (PMID 36309492, 2022). "Overall, CD80 was upregulated upon LOAd703 infection, whereas CD86 expression was rather stable." (PMID 33666760, 2021). "Importantly, CD86, which was significantly expressed in CP pDC, was further enhanced in CP-AS indicating that asymptomatic infection with SARS-CoV-2 strongly activates pDC." (PMID 34473805, 2021). "Consequently, during infection or inflammation, APCs upregulate CD86 and CD80 and both signals, TCR and CD28, are activated, so that T-cells perform target killing, with long-term persistence." (PMID 34771581, 2021). "In addition, these cells displayed elevated expression of CD80 and CD86 in the blood and spleen after 30 days of infection, which remained high in the spleen, and particularly in the MLN, after 60 days." (PMID 34685494, 2021).
infection (continued). "BC-3 cells appeared to have a distinct phenotype with no expression of CD80 and CD86, which is likely caused by their inherent infection with Kaposi's sarcoma-associated herpesvirus." (PMID 33666760, 2021). "During infection with E. histolytica, mice showed differential expression of CD86 and CX3CR1." (PMID 32651360, 2020). "In addition, L363 cells expressed the T cell costimulatory molecule CD86 and upregulated HLA-DR expression upon infection with the armed viruses." (PMID 32355275, 2020). "Moreover, following in vitro infection, pDCs expressed five- to tenfold higher levels of the co-stimulatory molecule CD86, likely reflecting activation of potent cell-intrinsic viral immune recognition pathways in pDCs." (PMID 32415086, 2020). "Upregulation of PD-L1 and CD86 was observed after infection (18.5- and 4.2-fold in mean fluorescence intensity compared with mock-infected cells, respectively), whereas HLA-DR, which was relatively highly expressed on uninfected cells, was only modestly upregulated (1.4-fold)." (PMID 32088771, 2020). "Burn injuries are highly susceptible to infection and in a human ex vivo burn model, thermal injury induced LC and DC emigration from the skin, with upregulation of MHC II and costimulatory molecules such as CD80, CD86 and CD40." (PMID 30696002, 2019). "Infection-induced de novo expression of CD11c was reported for PMN in different mouse infectious disease models and was found to be associated with elevated expression of MHCII, CD86 and CD62L." (PMID 30778357, 2019). "B cells transduced with vacGFP control virus also increased the expression of CD86 suggesting that infection of vaccinia virus alone could be stimulatory for B cells." (PMID 31736965, 2019). "Also, 4 weeks after infection, significantly higher percentage of activated, CD86 positive, CD11c+, CD11c+CD11b+, and CD11c+CD1d+ dendritic cells was detected in the livers of WT compared with Lgals3−/− mice." (PMID 31231399, 2019). "Moreover, while the infection also maintained low the expression of CD86, it increased that of CD206, in accordance with previous data." (PMID 31969878, 2019). "Interestingly, there was also a continuous up-regulation of the activation markers CD86 and HLA-DR on B cells during this acute period, returning to pre-infection levels by day 28 post-infection." (PMID 29215081, 2017). "Importantly, CD103−CD8− cDCs displayed a strong increase in CD86 expression upon infection with Yptb-WT, reflecting their activated phenotype." (PMID 28378044, 2017). "Together, the data indicate that 17-AAG might down regulate pro-inflammatory cytokine/chemokine production of host macrophages, without altering the induced immune activation markers like MHCs and CD86 during infection." (PMID 28067803, 2017). "Moreover, dendritic cells from Il22−/− mice expressed a higher amount of the costimulatory ligand CD86 upon infection." (PMID 27311945, 2016). "Flow cytometric analysis showed that only 40% of infected DCs were double positive for CD11c and CD86 after LPS stimulation (infection time: day 2); this percentage was significantly less than that observed in the mock-infected DCs after LPS stimulation (p < 0.01)." (PMID 26830017, 2016). "Similarly, the number of CD11c+MHCII+CD86+ cells was higher in La infection compared to Lb infection at 4 and 8 weeks PI." (PMID 27073297, 2016). "Infection with H1N1pdm09 increased the expression of HLA-DR and CD86." (PMID 25831059, 2015). "Thus, we examined the expression of MHC class II and co-stimulatory molecules CD80 and CD86 on PECs from immunized mice post-infection." (PMID 26114641, 2015). "We investigated whether the expression of CD80 and CD86, monocyte ligands for co-stimulatory molecules, was modified after 72 hours of infection with Y strain or Col cl1.7." (PMID 26147698, 2015). "Interestingly, infection with x31/Ova demonstrated relatively low CD86 MFI levels, a similar profile to that of inactivated virus." (PMID 26161083, 2015).
infection (continued). "We therefore wanted to independently evaluate the role of Tregs during recovery and in particular whether depletion of Treg cells in vivo at this late time point following infection (i.e. day 8–10 p.i.)would mimic the effect of CD86 blockade." (PMID 25144228, 2014). "Indeed, the activation of colonic CD45+MHCIIhiCD11c+F4/80−CD11b+ DCs, co-stimulatory molecules, CD80/CD86, and co-inhibitory, B7-H1, were unchanged or significantly depressed during infection, suggesting inhibition of immune functions." (PMID 24945934, 2014). "On day 21 of infection, decreases in the expression levels of CD86 and F4/80 were noted." (PMID 24312297, 2013). "The CD86 expressed in these cells was also up-regulated following infection (middle)." (PMID 23555767, 2013). "Furthermore, the total numbers of CD11c+ MHC II+ and CD11c+ CD86+ cells in the spleen were also increased by infection, although only the latter attained statistical significance." (PMID 23556020, 2013). "Similarly, the density of CD86 on HIV-GFP + MDM exceeded that on bystander cells at day 21–28 post-infection." (PMID 24341794, 2013). "The down-modulation of CD80/CD86 in chronic phase of the infection suggests that mycobacteria may actively exploit this pathway to anergize the T cells." (PMID 22719245, 2012). "Remarkably, B cells in infected TLR7-deficient mice upregulated CD69 and CD86 early in infection, but failed to develop into germinal center B cells." (PMID 21998589, 2011). "Through the analysis of correlation, both CD80+ pDCs (r = 0.462, P = 0.003) and CD86+ pDCs (r = 0.359, P = 0.023) were found to show a positive correlation with the time of infection, which seems to imply that more and more pDCs are activated following disease progression." (PMID 22174949, 2011). "In addition, the Dogon children undergoing infection had a decreased expression of CD86 on BDCA-2+ DCs as compared to their uninfected peers (p = 0.0003)." (PMID 21483827, 2011). "To assess whether infection resulted in a generalised activation of mucosal-associated B cells, we also measured expression of CD69 and CD86, two surface markers up-regulated on activated B cells." (PMID 20306466, 2010). "However, transcriptional changes in CD86 following infection exhibit strain-specific differences." (PMID 40817451, 2025). "Similarly, infection of DCs with a low pathogenic tick-borne flavivirus (Langat virus, LGTV) was reported to inhibit DC activation through defective IL-12 production and weak up-regulation of CD40, CD86, and MHC class II surface expression." (PMID 37707204, 2023). "Importantly, the analysis of costimulatory marker CD86, that was significantly expressed in pDC from critically ill patients and further enhanced in cells of asymptomatic subjects, indicated that pDC are strongly activated during asymptomatic infection." (PMID 34473805, 2021). "One alternate explanation could be that LPMs are replaced by SPMs or monocytes, as these cell subsets exhibit similar F4/80 and CD11b expression during the recovery phase, with LPM and SPM characterized by relatively comparable expression of MHC II and CD86 at later times post-infection." (PMID 33767688, 2021). "The results indicated that IL-6, IL-10, TNF-α, TGF-β, and iNOS expression in the infection group was significantly higher than in the control group, an increase of 1.2-fold, 0.29-fold, 0.32-fold, 0.12-fold, and 3.95-fold, respectively, as well as an increase of CD86 (P = .891) and CD206 (P = .303)." (PMID 30170447, 2018). "By contrast, in Lb infection a low number of CD86-activated DCs was detected in popliteal lymph nodes, and this was associated with an effective immune response, mediated by IFN-γ, and, consequently, the number of parasites drastically decreased during the course of infection." (PMID 27073297, 2016).
infection (continued). "In relation to the role of STAT-6 in CTL responses, it has been reported that the activation and function of CTL may be impaired in STAT-6−/− mice during infection with the intracellular parasite Toxoplasma gondii, likely as a consequence of reduced levels of CD86 expression on DC." (PMID 25751266, 2015). "Apart from age, infection status, bednet possession and gravidity, the immunological variables retained for multivariate analyses as a function of univariate analyses were monocyte frequency, monocyte CD86 expression, B cell HLA-DR expression, Treg and Teff freqeuncy." (PMID 23239967, 2012). "Interestingly, the reduction in CD86 could be accounted for by a paucity of CD86hiCD8αint cells, which are relatively diminished following infection." (PMID 19766674, 2009). "Blocking the CD28 ligands CD80 and CD86 in B6 mice reproduced the CD28ko phenotype following MmuPV1 infection and markedly reduced CD28 expression, implicating the CD28-CD80/CD86 axis in delayed viral clearance." (PMID 41805718, 2026). "During early kidney injury, M1 macrophages, induced by IFN‐γ and pro‐inflammatory signals, highly express iNOS and CD86, releasing IL‐1β, IL‐6, and TNF‐α to combat infection." (PMID 41527491, 2026). "Notably, CD86 exhibited divergent correlation patterns between macrophages and the overall cellular population, displaying negative correlation specifically within macrophages despite positive correlation across total cells, indicating macrophage-specific regulatory mechanisms during infection." (PMID 40723441, 2025). "Similar results were seen in splenic CD8α− cDCs, which are likely type 2 conventional dendritic cells (cDC2s), though there was a decrease in CD86 expression in PEP-null and PEP-R619W splenic CD8α− cDCs compared to PEP-WT post-infection." (PMID 40791464, 2025). "Levamisole and 25–100 mg/kg baicalin upregulated the mRNA expression of iNOS and CD86 and attenuated the levels of ARG1, IL-10, and CD163 in the spleen, in contrast with the infection group (p < 0.05)." (PMID 40427533, 2025). "After infection with the parasite, the expression levels of CD83, CD86, MHC-I, and MHC-II markers on splenic DCs increased." (PMID 38038457, 2024). "On the seventh day post-infection, the LV-NLRP12 group sustained an increased macrophage count in the dLNs but with a reduced percentage of CD86 positivity, indicating a potential shift towards promoting corneal repair functions." (PMID 39119293, 2024). "We observed that infection of WT BMDC led to an upregulation of CD86 compared with mock BDMC, and this upregulation upon infection was significantly reduced in Ifnlr1–/–." (PMID 38973611, 2024). "It has been shown that the infection of murine macrophages or DC with L. mexicana inhibits IL-12, while in DC, it delays maturation by inhibiting MHCII, CD86, and CD54 expression." (PMID 38787051, 2024). "The mean fluorescence intensity (MFI) of CD86 and CD206 expression on MHC-II+ recruited macrophages both peaked at 6 h and then steadily decreased until 24 h post infection." (PMID 38951957, 2024). "The genes for which the expression was higher in the lungs of WT than those of IFN-γR−/−mice in response to H37Rv infection included Mhc-II, CD274, Cd86, and Cd40, which are all involved in the synapse between antigen-presenting cells and T cells." (PMID 38803236, 2024). "This co-culture revealed that infection with H. pylori at the apical side of the mucosoid robustly activates DCs cultured at the basal side, as indicated by increased CD80, CD86, and PD-L1 expression." (PMID 39288239, 2024). "D609‐treated BMDCs exhibited a significant reduction in the mean fluorescence intensities of costimulatory molecules, including CD80, CD86, CD40, and the differences in the reduced levels of costimulatory molecules were more pronounced after infection." (PMID 39692711, 2024).